STAT3 (signal transducer and activator of transcription 3)
Diseases named in the same sentence as STAT3 in open-access papers (continued):
Sharing a sentence is not in itself a finding about the gene and the disease.
tumor (continued). "However, in many tumors, STAT3 is constitutively activated, closely associated with tumor malignancy." (PMID 40975978, 2025). "Importantly, these results support the concept that STAT3-targeted therapies have the potential to disrupt the transcriptional programs underlying immune cell transformation in the tumor microenvironment." (PMID 41514627, 2025). "Moreover, RESV downregulated STAT3 in vitro, thereby inhibiting M2-like polarization of tumor-associated macrophages (TAMs) and suppressing the proliferation of LC cells." (PMID 40948874, 2025). "The ability of resveratrol to modulate the tumor microenvironment, particularly by influencing tumor‐associated macrophages and immune responses, opens avenues for exploring immune modulation alongside STAT3 inhibition." (PMID 40860906, 2025). "Key pathways such as the Wnt/β-catenin, VEGF, PI3K/AKT, and JAK2/STAT3 pathways are central to endothelial cell proliferation, migration, and vascular maturation, whereas interactions with tumor-associated macrophages (TAMs) and pericytes further remodel the TME to support neovascularization." (PMID 40438141, 2025). "A diminished pro-inflammatory milieu may reduce the activation of survival pathways such as nuclear factor-kappa B (NF-κB) and STAT3, which are associated with chemoresistance and tumor progression." (PMID 40142281, 2025). "In addition, TTI-101, an inhibitor targeting STAT3, significantly inhibited tumor growth and metastasis in a SMARCB1-deficient tumor model." (PMID 39995416, 2025). "Additionally, this study demonstrated that PD1-induced FAO is partly mediated by STAT3 in tumor-associated T cells." (PMID 40612678, 2025). "Additionally, Ruxolitinib suppresses pancreatic cancer progression by attenuating the pro-tumor effects of tumor-associated macrophages through inhibition of the STAT3 signaling pathway." (PMID 40909292, 2025). "Moreover, depression promotes tumor-associated macrophage infiltration through neuropeptide Y signaling and accelerates tumor progression via activation of the IL-6/STAT3 pathway." (PMID 41409248, 2025). "Detected STAT3 activity in BC cells is associated with tumor cell migration." (PMID 40841364, 2025). "Notably, the EMT pathway mediated by CAFs and the STAT3 pathway associated with MDSCs represent critical hubs that link immunosuppression to tumor progression." (PMID 41333481, 2025). "Additionally, STAT3 is involved in regulating tumor-associated angiogenesis and epithelial–mesenchymal transition, both of which are key steps in tumor metastasis." (PMID 40989587, 2025). "In addition to intrinsic STAT3 activation, tumor-associated macrophages (TAMs) exacerbate muscle degeneration by secreting pro-inflammatory cytokines, particularly IL-1α and IL-6, which activate STAT3 signaling in muscle fibers." (PMID 40704145, 2025). "The STAT3 inhibitor TTI-101 was shown to effectively inhibit tumor growth in SMARCB1-deficient BLCA patient-derived xenograft mice without significant weight loss, providing a strong preclinical rationale for using TTI-101 as a therapeutic strategy for SMARCB1-deficient BLCA." (PMID 40115023, 2025). "Furthermore, HIF-1α-induced STAT3 activity enhances the immunosuppressive functions of tumor-associated macrophages (TAMs) and Tregs, contributing to immune evasion." (PMID 39981236, 2025). "MDSCs are CD11b+, whereas the immature mo-MDSCs are characterized by the Ly6Chigh and Ly6G- phenotype, and both cell types may transform into tumor-associated macrophages under the STAT3 signaling." (PMID 40136652, 2025).
tumor (continued). "The STAT-3 protein is involved in the regulation of cellular processes, including the cell cycle, cell proliferation, cell apoptosis, and tumor development, while the constitutive activation of STAT-3 has been reported to be associated with a poor prognosis for various types of cancer." (PMID 40564098, 2025). "Furthermore, STAT3 is implicated not only in tumor initiation but also in metastasis, as it regulates pathways that promote cancer cell migration and immune evasion." (PMID 40625361, 2025). "The JAK/STAT signaling pathway plays a central role in regulating tumor cell proliferation, survival, immune evasion, and inflammatory responses.Aberrant activation of this pathway, particularly through STAT3, has been implicated in the pathogenesis and progression of ccRCC." (PMID 41296440, 2025). "Given that surface molecules and protein mediators involved in T cell proliferation and activation are upregulated in STAT3-deficient neutrophils, we next assessed whether these cells can effectively modulate T cell responses in tumor-bearing mice." (PMID 40885734, 2025). "Furthermore, how CTRP6 interfaces with immune signaling—particularly NF-κB, STAT3, and tumor-associated macrophage polarization—remains poorly understood." (PMID 41228203, 2025). "Additionally, PTEN loss promotes PI3K signaling and, through the BMX/STAT3 pathway, contributes to tumor cell survival and metastasis." (PMID 40303296, 2025). "For example, cetuximab induces ICD by directly triggering ER stress on the cell surface to promote DC phagocytosis; it also indirectly induces the polarization of tumor-associated macrophages (TAMs) by inhibiting IL-6 expression via the NF-κB and STAT3 pathways." (PMID 41314288, 2025). "Notably, STAT3 is implicated in the promotion of tumor growth and the induction of immunosuppression." (PMID 38699644, 2024). "Importantly, activation of STAT3 signalling has been found to induce a switch from the less aggressive proneural to the more aggressive mesenchymal tumour subtype associated with chemoradiotherapy-resistance and recurrence in GBM." (PMID 38615034, 2024). "Activation of STAT3 in tumor cells causes increased expression of PDL1 resulting in immune evasion." (PMID 38424636, 2024). "Moreover, by regulating tumor metabolism and the specialization of cancer-associated fibroblasts (CAFs), STAT3 can promote a microenvironment which supports tumor growth, development, and progression." (PMID 38464736, 2024). "Furthermore, activation of the STAT3/NFκB pathway by CAF-secreted IL-6 induces CXCR7 expression in tumor cells, which has been associated with drug resistance." (PMID 39092186, 2024). "Moreover, loss of VDUP1 enhanced the active forms of NF-κB p65 and STAT3, accompanied by a significant increase in the nuclear translocation of phosphorylated p65 to the tumor tissues in CAC model mice compared to that in WT mice." (PMID 39272794, 2024). "Recent studies in a TNBC mouse model show that inhibition of STAT3 not only reduces the elevated levels of PD-L1 expression, which serves to bind and inhibit T cell function, but also directs the phenotype of tumor associated macrophages (TAM) towards an anti-tumorigenic M1 phenotype." (PMID 39200368, 2024). "Chitin significantly reduced primary tumor progression in the 4T1-based model by decreasing the high production of CLPs that originate from tumor-associated neutrophils (TANs) and Stat3 signaling, prominently affecting the CHI3L1 and CHI3L3 primary tumor levels." (PMID 38605414, 2024). "Furthermore, it has been observed that activated STAT3 can induce a phenotypic transition in tumor-associated macrophages (TAMs) from M1 to M2 via NF-κB signaling within the tumor microenvironment (TME)." (PMID 38920657, 2024). "We hypothesise that a feedback loop arises, whereby cytokines secreted by CAFs activate STAT3 in the tumor cells, which causes transcription of genes which promote stromal cell proliferation and recruitment of CD66b + cells to the TME." (PMID 38424636, 2024).
tumor (continued). "For instance, the STAT3 less-expressed M-MDSCs can differentiate to anti-tumor DCs, and this complete elimination may cause decreased DCs in the OS-TME, leading to non-beneficial effects of OS treatment." (PMID 38399305, 2024). "Blocking STAT3 activation inhibits tumor-associated macrophages' polarization to M2 phenotype." (PMID 38274367, 2024). "Furthermore, the anti-tumor effect of PTPRO in LUAD was significant but compromised in STAT3-deficient cells." (PMID 38182570, 2024). "Furthermore, we found a strong association correlation between +CD163 + CD204M2-TAM with STAT3 and NF-κB signaling pathways, as well as with factors linked to tumor growth, dissemination, and immunosuppression." (PMID 39061137, 2024). "It has been suggested that persistent activation of STAT3 is linked to tumor-associated angiogenesis, but underlying mechanisms remain unclear." (PMID 38576624, 2024). "Moreover, IL-11 secreted from cancer-associated fibroblasts in response to TGF-β activates gp130/STAT3 signalling to promote the survival of metastatic tumour cells." (PMID 38600086, 2024). "Mechanistically, piperine-induced ROS generation is associated with oxidative stress, which can lead to oxidative DNA damage and activate pro-inflammatory pathways such as NF-κB and STAT3, both implicated in inflammation-driven carcinogenesis and tumor progression." (PMID 39736510, 2024). "Excessive STAT3 activity is associated with higher mortality rates and peritumoral (Crohn’s-like) lymphocytic structures, implicating a role for STAT3 in regulating immune-mediated tumour responses." (PMID 38600086, 2024). "When they shift towards the CD163 + 204 + M2-TAM phenotype through the activation of the signal transducer activator (STAT3) pathway caused by an immunosuppressive cytokine loop, they promote immunosuppression, drug resistance, tumor progression, and metastasis." (PMID 39061137, 2024). "IL-6 has long been associated with tumour growth through the activation of the STAT3 pathway." (PMID 39516433, 2024). "In addition, overexpression of YAP1 induces the polarization of macrophages into the M2 phenotypes (tumor-associated macrophages) by regulating different genes such as iNOS, MerTK, IL-10, STAT3, CD163, CD206, Arg-1, CD86, and TNF-α in the naive macrophages." (PMID 39630608, 2024). "Intrinsic mechanisms include JAK2/STAT3 signaling transduction and intracellular STAT3’s direct transcriptional regulation of genes associated with tumor progression, such as those promoting the differentiation and cytotoxic functions of tumor-specific T cells." (PMID 38920657, 2024). "Recent scientific discoveries have shed light on PDIA3's influential role in modulating the behavior of tumor-associated macrophages, in particular, its regulatory capacity over the STAT3/PD-1 (signal transducer and activator of transcription 3/programmed cell death protein 1) signaling axis." (PMID 38761176, 2024). "Moreover, tumor-associated neutrophils can produce IL-17a to promote cancer EMT through JAK2/STAT3 signaling." (PMID 38216787, 2024). "Cytomegalovirus could present as a causative agent to GBM through ARG2 upregulation and STAT3 signaling, which is often used as an early tumor biomarker." (PMID 38612552, 2024). "In addition, C/EBPβ-induced secretion of pro-inflammatory cytokines interleukin-6 (IL6) creates a positive feedback loop that activates the STAT3 signaling pathway in tumor-associated macrophages and promotes migration and invasion of lung adenocarcinoma." (PMID 39858431, 2024). "Thus, our data suggests that genetic depletion of STAT3 in HStCs is sufficient to inhibit myMAF activation and is associated with an improved immunostimulatory anti-tumour response in PDAC liver metastasis." (PMID 38678021, 2024). "Interestingly, the STAT3-stimulating activities of IL-6 have been also recently associated to the suppression of T-cell anti-tumor activities." (PMID 39281678, 2024).
tumor (continued). "Moreover, tumor-associated B cells stimulate ECs via the signal transducer and activator of transcription 3 (STAT3)-YAP/TAZ signaling promoting tumor angiogenesis." (PMID 38426109, 2024). "Therefore, excessive activation of STAT3 in cancer cells, as well as in cells in the inflammatory tumour microenvironment (TME), can cause an inflammation-driven repair response." (PMID 38760429, 2024). "Similarly, the senescent TME, enriched in adenosine due to senescent tumor cells stimulating CD73 expression on tumor-associated macrophages via IL-6 and the JAK/STAT3 pathway, impedes anti-tumor immunity." (PMID 39461979, 2024). "STAT3 activation, which is associated with cytokine signaling in immune cells, has been observed in several malignancies, both within cancer cells, but also, within the tumor microenvironment immune cells." (PMID 38916963, 2024). "Notably, QRHX inhibits inflammation and the CXCL12/CXCR4/JAK2/STAT3 signaling pathway, thereby modulating tumor-associated macrophages in murine models and suppressing tumor growth." (PMID 38920657, 2024). "To test this hypothesis, we sought to elucidate the impact of SMARCB1 loss and subsequent STAT3 pathway activation on bladder orthotopic tumor growth, metastasis, and BLCA disease-specific survival." (PMID 38355560, 2024). "Because α-hederin inhibited the phosphorylation of JAK2 and STAT3, which is implicated in tumor EMT and metastasis, α-hederin could be regarded as a promising candidate for the intervention of colon cancer metastasis." (PMID 38339403, 2024). "Since p27/STAT3/cJun complexes activate gene drivers of stem cell expansion and repress genes associated with differentiation, we next assayed effects of p27 on tumor-initiating ability in vivo." (PMID 38886396, 2024). "Notably, STAT3 has been implicated as a malignant factor in CTCL due to its ability to inhibit apoptosis of tumor cells." (PMID 39963655, 2024). "STAT3 is strongly associated with tumor development and progression." (PMID 39001513, 2024). "Furthermore, the loss of RUNX1 affects the expression of EGFR and STAT3, thereby regulating the downstream pathways and ultimately regulating the function of tumor cells." (PMID 37760803, 2023). "In addition, studies on the mechanism of Hsp110 in tumor have shown that the combination of abundant Hsp110 with STAT3 causes activation of downstream STAT3 signaling via a specific increase in STAT3 phosphorylation." (PMID 37978368, 2023). "This study also aimed to describe differences in the underlying biology of tumours with high protein expression of IL6/JAK/STAT3 using TempO‐Seq transcriptional analysis in a subset of patients (n = 14) and histological scores of the tumour microenvironment (TME) in the full cohort." (PMID 37199043, 2023). "In addition to maintaining the stemness of CSCs, JAK/STAT3 signaling also leads to CSC-associated tumor metastasis by regulating the EMT process." (PMID 37853437, 2023). "Deregulation of the STAT3 transcription factor has been linked to the genesis of diverse tumor types, and has also been implicated in tumor migration, metastasis, and refractoriness to both chemotherapeutic agents as well as microenvironmental/stromal cell forms of resistance." (PMID 37126127, 2023). "Furthermore, tumor-associated regulatory T cells (Tregs) express the IL-23 receptor, which stimulates the expression of Stat3 in dendritic cells, leading to upregulation of the Treg-specific transcription factor Foxp3 and the immunosuppressive cytokine IL-10." (PMID 37685766, 2023). "PAK4 influences genes linked to stem cell traits, affecting tumour sphere formation through STAT3." (PMID 38067120, 2023). "Furthermore, in the TME, studies have indicated the role of tumour-associated macrophages in promoting tumour growth, with the STAT3 pathway being a key player." (PMID 37895205, 2023).
tumor (continued). "Besides, CD45 SUMOylation via SENP1-deficiency facilitates STAT3 dephosphorylation, suppressing tumor development by myeloid-derived suppressor cells (MDSC) infiltration." (PMID 37415251, 2023). "Activation of STAT3 by the IL-6 secreted in head and neck squamous cancer cells in tumor-associated endothelial cells has nominated this factor to be a part of CSCs and ECs network, considering the role of IL-6 in the induction of glycolytic pathway, as a glycolytic phenotype in ECs cells." (PMID 37328876, 2023). "Furthermore, increased expression of STAT1 and STAT3 in tumor tissue implicated adverse prognosis whereas higher STAT4 or STAT5 expression meant improved survival." (PMID 36968603, 2023). "TME deconvolution and cell interaction analyses allow us to identify the chemokine CCL18 secreted by tumor associated macrophages could promote tumor cell proliferation via JAK2/STAT3 signaling pathway and lead to poor prognosis of ESCC." (PMID 36850011, 2023). "Similarly, tumors induced by cancer cells stably expressing STK24+shnc were much bigger than tumors induced by cancer cells stably expressing vector+shnc, with the loss of STAT3 reversing STK24-mediated tumor progression." (PMID 36720310, 2023). "The selective pressure on STAT3 loss during metastatic progression suggests that this step may be required to facilitate tumor dissemination." (PMID 37573301, 2023). "Signalling and chronic-tumour dependent hematopoietic stimulation through the release of CSF-2, CSF-3, IL-6, and other cytokines are associated with the activation of STAT3 signalling and expression of c/EBPβ transcription factor which sustain MDSC expansion and immune suppressive features." (PMID 36161514, 2023). "These particular cytokines regulate transcription factors such as the signal transducer and transcription activator 3 (STAT3) in tumor cells, especially in gliomas, resulting in tumor-causing immune responses and also leading to an inhibition of T cell activation and proliferation." (PMID 37759505, 2023). "Furthermore, activated STAT3, which is associated with a poor prognosis in cancer, participates in tumor progression via IL-10 and IL-6, and tightly regulates M2 polarization and activation status." (PMID 37759870, 2023). "STAT3 was detected in the tumour cell cytoplasm, nuclei and also in the tumour‐associated stroma." (PMID 37199043, 2023). "Besides, STAT3 stimulates the polarization of tumor-associated macrophages (TAMs) towards the M2 phenotype, as well as PD-L1 expression, which also facilitates tumor progression." (PMID 36675114, 2023). "Likewise, Let-7 and miR-122 have been found to be downregulated by HBx; these miRNAs are associated with cell proliferation and tumor growth by targeting signal transducer and the activator of transcription 3 (STAT3) and cyclin G1, respectively." (PMID 38139051, 2023). "Indeed, FAP activates inflammatory CAFs by triggering STAT3, which is an important transcription factor involved in tumor-associated inflammation." (PMID 38313431, 2023). "Abnormal STAT3 activation is implicated in tumor malignancy." (PMID 36672337, 2023). "KT-333 causes a decrease in STAT3 levels in vitro and in vivo and induces tumor cell death." (PMID 37496997, 2023). "However, curcumin significantly reduced the expression of NF-kB, COX-2, and phosphorylated STAT3, which are implicated in tumor-/angiogenesis and growth and are over-expressed in pancreatic and other cancers." (PMID 36829437, 2023). "STAT3 activation was detected in various tumors in association with the proliferation, invasion, and angiogenesis of malignant cells and the inhibition of anti-tumor immunity." (PMID 37860678, 2023). "We have shown that STAT3 acts as a tumor suppressor upon PTEN loss, thus overcoming senescence." (PMID 37573301, 2023).